PTH (parathyroid hormone)
Diseases named in the same sentence as PTH in open-access papers (continued):
Sharing a sentence is not in itself a finding about the gene and the disease.
vitamin D deficiency (continued). "Vitamin D deficiency might contribute to the development of TMD through increasing the parathyroid hormone." (PMID 32872653, 2020). "Low vitamin D levels are frequent in patients with this condition, and evidence suggests that vitamin D deficiency in these patients is associated with more aggressive disease, greater levels of PTH and bone turnover markers, and a higher risk of hungry bone syndrome following parathyroidectomy." (PMID 32813765, 2020). "Furthermore, vitamin D deficiency can activate the parathyroid to induce the release of parathyroid hormone, which was thought to increase serum uric acid level." (PMID 33330592, 2020). "As for PTH, the average levels in both of the treatment groups were above normal values (10–55 pg/mL); this may be due to a poor calcium intake, vitamin D deficiency or estrogen deficiency." (PMID 32722015, 2020). "It has been reported that AD patients are at increased risk of falling and hip fracture due to weakened motor function and balance, and that AD and hip fractures share risk factors such as calcium imbalance, vitamin D deficiency, and elevated parathyroid hormone levels." (PMID 33364244, 2020). "Patients with vitamin D deficiency may also be asymptomatic, with normal calcium and elevated PTH concentrations." (PMID 31914999, 2020). "Therefore, the recruited subjects with vitamin D deficiency and slightly elevated PTH concentrations were likely to be true SHPT patients." (PMID 31914999, 2020). "Clinically important PTH elevations were observed in vitamin D deficiency, where revised reference ranges with a higher URL may be appropriate." (PMID 31273631, 2019). "Vitamin D deficiency causes elevation of PTH, which also affects the storage of fat." (PMID 30975093, 2019). "Those points at which 25(OH)D maximally suppresses or rapidly raises PTH could be targeted markers for definition of vitamin D deficiency." (PMID 31770397, 2019). "In the MORE study, the groups with vitamin D deficiency (serum 25OHD <25 nmol/L, n = 297 and 25OHD 25 to 50 nmol/L, n = 1721) both show significantly higher serum PTH (4.8 ± 2.2 and 4.1 ± 1.8 pmol/L, respectively) compared with people with 25OHD >50 nmol/L (n = 4982, serum PTH 3.5 pmol/L)." (PMID 30321335, 2019). "Hence, we need further research to clarify the clinical value of PTH in identifying vitamin D deficiency/insufficiency." (PMID 31360166, 2019). "Some references consider PTH reduction to be one of the targets for treating vitamin D deficiency." (PMID 30735332, 2019). "These could range, as often is the case with normal aging, from poor calcium retention, Vitamin D deficiency, or impaired parathyroid hormone secretion, and/or body composition/sub-optimal food intake." (PMID 31037056, 2019). "In conclusion, our results confirm that vitamin D deficiency induces AmB/LE nephrotoxicity possibly due to impaired renal function accompanied by tubular injury, the arising of hypertension, alterations in the PTH-Klotho-FGF-23 signaling axis and water balance dysfunction." (PMID 31295336, 2019). "Vitamin D deficiency occurs frequently in the general population, with an estimated prevalence of 41.6% among US adults, increasing to 82.1% in black individuals, and elevated PTH secretion is associated with vitamin D deficiency." (PMID 31273631, 2019). "Using upper and lower cut-offs of biomarkers we describe a phase that can be regarded as sub-clinical hypoparathyroidism or impending hypoparathyroidism where there is inappropriately normal PTH levels in response to either vitamin D deficiency or low Ca levels." (PMID 31360455, 2019). "However, 7% of our participants who experienced vitamin D deficiency and elevated PTH had lower BMD at one of the two sites." (PMID 29750126, 2018). "Thus, secondary hyperparathyroidism refers to elevation of PTH resulting from low 25(OH)D and represents a functional vitamin D deficiency, encompassing a sub-group of those with low 25(OH)D concentrations." (PMID 30018262, 2018).
vitamin D deficiency (continued). "Higher geographic latitude or dark skin may be associated with a higher prevalence of vitamin D deficiency, higher PTH levels, and more prescriptions of activated vitamin D." (PMID 30400889, 2018). "Interestingly, about 70% of participants with mild vitamin D deficiency had normal PTH levels, and about 10% of diabetic patients with severe vitamin D deficiency showed low PTH levels." (PMID 30723655, 2018). "Parathyroid hormone (PTH) levels increase with vitamin D deficiency and might be an important indicator for the bone remodeling." (PMID 29271084, 2018). "In addition, diabetic patients with vitamin D insufficiency had a higher concentration of PTH than those with mild vitamin D deficiency." (PMID 30723655, 2018). "We also determined whether vitamin D deficiency as determined using published cut offs translated into a functional deficiency by assaying PTH, total calcium and inorganic phosphate." (PMID 30305067, 2018). "In the next stage, when the severity of vitamin D deficiency continues to progress and PTH secretion is further stimulated, a PTH resistance gets overcome leading to improved calcemia but also to hypophosphatemia and clinical and radiological manifestation of rickets." (PMID 29904370, 2018). "In addition to the relationship between PTH and GFR, vitamin D deficiency, which is also related to PTH secretion, is prevalent in subjects with CKD49,50." (PMID 29348466, 2018). "However, after vitamin D treatment her PTH level normalized (it was probably secondary to vitamin D deficiency)." (PMID 29499646, 2018). "It should also be noted that the regulation and action of parathyroid hormone (PTH) may be disturbed by vitamin D deficiency, particularly in infancy." (PMID 29699378, 2018). "One might expect that the genetic variants associated with low vitamin D levels would be associated with elevated PTH levels, since vitamin D deficiency often causes secondary hyperparathyroidism, with elevated PTH levels." (PMID 30576350, 2018). "Vitamin D levels below 30 ng/mL was associated with a significant rise in PTH levels, suggesting that this cut off could be appropriate for defining Vitamin D deficiency in the population served by our laboratory." (PMID 30305067, 2018). "About 10% of diabetic patients with severe vitamin D deficiency had a low PTH level." (PMID 30723655, 2018). "A hallmark of vitamin D insufficiency/deficiency is elevated levels of parathyroid hormone (PTH)." (PMID 28726185, 2018). "Accordingly, we can speculate that the success of vitamin D supplementation on CVR lowering needs preventively a stratification of patients with vitamin D deficiency according to PTH plasma levels." (PMID 30662585, 2018). "Vitamin D deficiency due to limited sun exposure or inadequate amounts of dietary vitamin D decreases the efficiency of intestinal calcium absorption, resulting in increased parathyroid hormone (PTH) concentrations." (PMID 29750126, 2018). "Furthermore, smoking and alcohol consumption are known to affect parathyroid hormone, which controls the absorption of calcium, ultimately causing vitamin D deficiency." (PMID 28652922, 2017). "Third, serum PTH level is associated with vitamin D deficiency and depression." (PMID 28192445, 2017). "For example, Vitamin D deficiency may increase PD risk, and is a common finding in 22q11.2DS related to inadequate levels of parathyroid hormone secretion." (PMID 28430790, 2017). "It is historically known that vitamin D deficiency contributes to disturbed calcium metabolism with consequently increased parathyroid hormone (PTH) levels that may ultimately lead to rickets and osteomalacia." (PMID 28448457, 2017). "Vitamin D deficiency decreases calcium absorption from the intestinal tract and the kidneys, increases parathyroid hormone (PTH) concentration, and leads to osteolysis, which over time may lead to fracture." (PMID 29464131, 2017). "Serum PTH is a sensitive indicator of calcium and vitamin D deficiency." (PMID 28894263, 2017).
vitamin D deficiency (continued). "Understanding the mechanism(s) behind vitamin D metabolism in obesity may help individualize the treatment of vitamin D deficiency and PTH suppression." (PMID 28272298, 2017). "Then, another possibility is that relatively lower serum phosphate levels might be observed in subjects with relatively higher endogenous PTH levels in the presence of vitamin D insufficiency/deficiency." (PMID 26478225, 2016). "Both PTH and vitamin D play a crucial role in calcium metabolism, so it is impossible to absolutely exclude confounding factors such as primary hyperparathyroidism and secondary hyperparathyroidism due to vitamin D deficiency." (PMID 26871857, 2016). "In all cases, vitamin D deficiency produced disorders in calcium and PTH levels." (PMID 26827062, 2016). "In addition, a developing vitamin D deficiency is compensated for by increased activation of 1α-hydroxylase which results from increased secretion of PTH, thus restoring 1,25(OH2)D levels and thereby masking vitamin D deficiency." (PMID 27756244, 2016). "Considering that disturbances in calcium metabolism with a subsequent increase in PTH levels are a hallmark of vitamin D deficiency, we further evaluated whether vitamin D supplementation exerts any effect on these parameters." (PMID 27171112, 2016). "Therefore high PTH level due to vitamin D deficiency leads to AF resulting in intracellular calcium overload." (PMID 28210468, 2016). "Underlying mechanisms might include a decreased insulin sensitivity related with increased parathyroid hormone levels which, in turn, are associated with vitamin D deficiency." (PMID 26873590, 2016). "Vitamin D deficiency might activate the renin-angiotensin system, increase serum level of parathyroid hormone (PTH), and decrease insulin-like growth factor 1 (IGF-1) level." (PMID 25822845, 2015). "In addition, vitamin D deficiency was accompanied with activation of the renin-angiotensin-aldosterone system, and the associated increase of parathyroid hormone has been related to insulin resistance." (PMID 25807387, 2015). "Vitamin D deficiency or insufficiency leads to releasing of parathyroid hormone." (PMID 25802799, 2015). "Other studies have shown elevated PTH to be associated with HF, and left ventricular hypertrophy, possibly suggesting vitamin D deficiency, may be a marker of elevated PTH levels." (PMID 26435569, 2015). "Paricalcitol administration suppressed parathyroid hormone (p<0.001), elevated plasma calcium phosphate product (p<0.005) and induced an increase in calcification density (472 versus 200, p<0.005) similar to that seen with vitamin D deficiency." (PMID 24586387, 2014). "Hyperparathyroidism is linked to hypertrophy of cardiomyocytes and arterial stiffness and vitamin D deficiency may be predisposed to increased BP via elevated PTH and disturbed calcium homeostasis." (PMID 25325256, 2014). "One possible explanation could be the presence of secondary hyperparathyroidism due to vitamin D deficiency, as PTH causes predominantly cortical bone loss." (PMID 24721668, 2014). "PTH increases calcium release from bone into the blood through indirect stimulation of osteoclasts, making it a good indicator of bone turnover, and several disorders, including vitamin D deficiency, are characterized by elevated PTH." (PMID 24324827, 2013). "Vitamin D deficiency is prevalent in critically ill patients and may contribute to suboptimal clinical outcomes, but little is known about alterations of the calcium-parathyroid hormone (PTH)-vitamin D axis and prognosis in these individuals." (PMID 24073266, 2013). "Vitamin D deficiency leads to decreased intestinal Ca absorption and secondary increased PTH." (PMID 23029191, 2012). "Vitamin D deficiency appears to be related to an increase in parathyroid hormone levels and can predispose to essential hypertension and left ventricular hypertrophy, increased insulin resistance, and eventually to atherosclerosis and adverse cardiovascular events." (PMID 23346457, 2012).
vitamin D deficiency (continued). "Vitamin D deficiency may predispose to hypertension via elevation of PTH and disturbed calcium homeostasis, although the relationship between vitamin D and blood pressure is not consistent." (PMID 23781303, 2012). "Moreover, vitamin D deficiency is common in elderly people and can lead to secondary hyperparathyroidism and PTH-induced bone loss." (PMID 22466444, 2012). "For example, the recent interest in mineral and bone disease including vitamin D deficiency could explain the increased monitoring of phosphorus and PTH." (PMID 21406096, 2011). "Zeghoud et al29 have shown that supplementation with 1000 but not 500 IU/day of ergocalciferol for a month could normalize the PTH levels in infants with subclinical vitamin D deficiency." (PMID 21441679, 2011). "Vitamin D deficiency may increase the severity of primary hyperparathyroidism (presence of larger adenomas, higher PTH levels, and greater bone turnover)." (PMID 22111014, 2011). "This is the result of both its substantially higher concentration and the fact that even with a marked vitamin D deficiency, elevated PTH levels will maintain the conversion of 25(OH)D to 1,25(OH)2D, thereby sustaining 1,25(OH)2D levels within normal ranges, despite low reserves." (PMID 19807897, 2010). "Moreover, markers of baseline vitamin D deficiency and PTH levels in Saudi patients of variable disease severity need to be studied to explore the possibility of widespread vitamin D deficiency." (PMID 19561907, 2008). "Vitamin D deficiency may also reduce the effectiveness of PTH in increasing serum calcium." (PMID 41568160, 2026). "For instance, widespread vitamin D deficiency (25(OH)D <20 μg/L in 68% of T2D patients) may independently suppress osteoblast activity and amplify PTH secretion - potentially obscuring TyG-BMI’s true relationship with bone formation markers like TP1NP and osteocalcin." (PMID 41019332, 2025). "However, vitamin D deficiency is associated with increased concentrations of IL-17 and PTH." (PMID 39861482, 2025). "Furthermore, we found that PTH levels were significantly higher in vitamin D deficiency subjects." (PMID 40613069, 2025). "As vitamin D deficiency is common in PHPT due to PTH-mediated catabolism, its surgical correction could potentially enhance the anti-inflammatory effects of PTX through vitamin D’s immunomodulatory properties, including suppression of pro-inflammatory cytokines and promotion of immune tolerance." (PMID 40731865, 2025). "Thus, the alkaline phosphatase (ALP) indicators were increased by 2.3 times with vitamin D deficiency and by 1.2 times with insufficiency; parathyroid hormone—by 3.2 times with vitamin D deficiency and by 2.6 times with vitamin D insufficiency (p < 0.05, p < 0.001)." (PMID 40837675, 2025). "Furthermore, vitamin D deficiency is associated with elevated parathyroid hormone (PTH) levels, which may increase renal uric acid reabsorption and impair excretion." (PMID 40805984, 2025). "Osteoblasts and osteoclasts normally work together in bone repair, remodeling, and growth but this process is exaggerated under the influence of increased parathyroid hormone whether primary, due to a parathyroid adenoma, or secondary, as a result of vitamin D deficiency or chronic kidney disease." (PMID 39530344, 2025). "Moreover, in Western countries, the widespread biochemical screening, decreased prevalence of vitamin D deficiency, and the assessment of PTH levels as part of the evaluation for low bone mass, allow the recognition of pauci-asymptomatic forms of PHPT, particularly in this population." (PMID 38715334, 2024). "However, an elevated PTH with normocalcemia might have indirectly indicated a concomitant vitamin D deficiency, which, by recommendation, should be excluded in these cases." (PMID 39636417, 2024).
vitamin D deficiency (continued). "Patients with CKD often present with vitamin D deficiency and low levels of 25(OH)D, the predominant circulating form of vitamin D. A decrease in 25(OH)D level leads to reduced intestinal Ca absorption, decreased total Ca level, and elevated PTH level in the blood." (PMID 36309659, 2022). "Thus, vitamin D deficiency may significantly effect on the axis of PTH and cause secondary hyperparathyroidism." (PMID 35887903, 2022). "Vitamin D deficiency in the elderly people causes secondary hyperparathyroidism and increased risk of hip fracture, as low circulating levels of vitamin D increases parathyroid hormone (PTH) levels, which induce bone resorption and bone loss in elderly subjects." (PMID 36187112, 2022). "Moreover, elevated PTH was found as a result of vitamin D deficiency." (PMID 36014846, 2022). "Thus, Vitamin D deficiency with a consequent reduction in intestinal calcium absorption leads to the compensatory secondary hyperparathyroidism with hypertrophy of the parathyroid glands and increased bone and renal calcium reabsorption induced by PTH." (PMID 31492617, 2021). "Therefore, measurements of 1,25-dihydroxyvitamin D may appear normal even in individuals with vitamin D insufficiency or deficiency due to increased parathyroid hormone and the activity of 1α hydroxylase." (PMID 33652653, 2021). "Also, lower glomerular filtration rate, low intact parathyroid hormone (iPTH) levels, and renal tubular unresponsiveness to PTH, especially in the first three days of life, could have led to hyperphosphatemia alongside vitamin D deficiency." (PMID 33304688, 2020). "However, in survivors of ALL, the finding of vitamin D deficiency and hyperparathyroidism is of importance in the context of the ongoing debate whether elevated PTH levels may increase the risk for relapse in hematological and non-hematological malignancies." (PMID 32984219, 2020). "Therefore, vitamin D deficiency as well as renal failure, both conditions leading to secondary hyperparathyroidism, should be ruled out or taken into consideration when establishing a reference range of PTH." (PMID 32148490, 2020). "Bone alkaline phosphatase was higher in patients with vitamin D deficiency (29.50 ± 14) than in patients with insufficiency (23.47 ± 8.1) and sufficiency (22.14 ± 9.7) (p = 0.0233 and 0.0440, respectively); probably due to the increased PTH in the former group." (PMID 33271814, 2020). "Because intact PTH concentration may begin to increase at an earlier stage of CKD in the presence of vitamin D deficiency, vitamin D status should be evaluated, even in the early stages of CKD, to mitigate hyperparathyroidism developing secondary to CKD or CKD-MBD." (PMID 32582730, 2020). "In addition, the proposed threshold of 20, 21–29, and 30 ng/mL 25 (OH) D is mainly derived from studies on role of vitamin D on calcium homeostasis, bone mineralization, and PTH levels, whereas the consequences of vitamin D deficiency on organs other than bone are not yet fully known." (PMID 32102427, 2020). "Vitamin D deficiency may lower serum Ca or increase PTH levels in PHPT." (PMID 32803112, 2020). "Further, the increase in PTH concentration may increase 1α,25(OH)2D3 concentration that, in turn, could exert a negative feed-back on hepatic synthesis of 25OHD thus contributing to worsen vitamin D deficiency." (PMID 31842281, 2019). "Moreover, investigations into the suitability of the current cut-off values for our population, long-term impact of vitamin D deficiency in infants, and biological significance of PTH as a marker of vitamin D deficiency are other important areas for future research." (PMID 31360166, 2019). "Interestingly, about 10% of diabetic patients with severe vitamin D deficiency had low PTH level." (PMID 30723655, 2018).